TTR (transthyretin)
Diseases named in the same sentence as TTR in open-access papers (continued):
Sharing a sentence is not in itself a finding about the gene and the disease.
cardiac amyloidosis (continued). "We customized our search to include any clinical studies that had evaluated Tafamidis’s role in treating transthyretin amyloid cardiomyopathy." (PMID 34703707, 2021). "For example, WT-TTR cardiac amyloidosis is solely composed of WT-TTR, and ATTTv amyloid deposits are mostly TTR variants." (PMID 34884963, 2021). "Apical sparing is observed both in patients with transthyretin cardiac amyloidosis and in those with amyloid light-chain amyloidosis." (PMID 33460030, 2021). "Tafamidis, an agent that stabilizes the TTR proteins, is approved therapy for TTR cardiac amyloidosis." (PMID 33993188, 2021). "The emergence of specific therapies for transthyretin cardiac amyloidosis (CA) warrants the need for a systematic review of the literature." (PMID 32969287, 2020). "Tafamidis (Vyndaqel, Pfizer Inc., New York, NY, USA) is the only TTR tetramer stabilizer approved for use in patients with TTR polyneuropathy and in patients with transthyretin amyloid cardiomyopathy." (PMID 33348885, 2020). "Further possible explanations also include the particular spectrum of TTR variants in Austria and more specific techniques, such as CMR, bone scintigraphy and/or EMB to detect cardiac amyloidosis." (PMID 32674397, 2020). "Endomyocardial biopsy verified the diagnosis of transthyretin cardiac amyloidosis (ATTR-CA) with Congo red staining of transthyretin fibrils." (PMID 32026266, 2020). "Cardiac amyloidosis (CA) is also common, particularly in elderly males, with wild-type transthyretin amyloid (ATTR) deposits seen in the heart at autopsy in 25% of patients aged 85 and over." (PMID 32267922, 2020). "TTR genotyping was available for 40 (70%) of the 57 patients with suspected ATTR cardiac amyloidosis." (PMID 32498921, 2020). "Only two types of proteins commonly affect the heart leading to an infiltrative cardiomyopathy: immunoglobulin light chain and transthyretin (TTR) cardiac amyloidosis (CA)." (PMID 33121442, 2020). "ATTR amyloid cardiomyopathy results from the accumulation of either wild-type (ATTRwt) or hereditary/mutated (hATTR) transthyretin protein." (PMID 32844347, 2020). "The effects of tafamidis were consistent across transthyretin genotypes (for those with hereditary transthyretin amyloid cardiomyopathy) and both the 80 mg and 20 mg tafamidis doses." (PMID 31942237, 2019). "Important biomarkers for cardiac amyloidosis are NT-proBNP (N-terminal pro brain natriuretic peptide) and Troponin T or I, which are elevated due to direct toxicity of the TTR amyloid and myocardial strain." (PMID 31083399, 2019). "The high population prevalence of the mutations in the transthyretin gene makes hereditary ATTR the most common form of familial amyloid cardiomyopathy and possibly the most common subtype of amyloid heart disease." (PMID 31452023, 2019). "Another example is cardiac amyloidosis, in which production and secretion of a mutant form of the transthyretin (TTR) protein by the liver into the bloodstream results in the accumulation of the mutant protein within the cardiac muscle." (PMID 31762718, 2019). "A Phase 2 clinical trial (NCT03702829) is currently underway: 24-Month Open Label Study of the Tolerability and Efficacy of Tegsedi in TTR Amyloid Cardiomyopathy Patients." (PMID 31117178, 2019). "Combined heart and liver transplant (eliminating pathologic transthyretin production) is also reasonable to consider in younger patients with hereditary forms of ATTR cardiac amyloidosis." (PMID 31452023, 2019). "Until the development of transthyretin stabilizers and RNA therapeutics, transthyretin amyloid cardiomyopathy treatment focused on symptom palliation and there was minimal impetus to diagnose this debilitating condition." (PMID 31942237, 2019). "Scintigraphy with 99mTc-DPD shows cardiac tracer uptake and is capable of diagnosing TTR cardiac amyloidosis in early stages before echocardiographic or even CMRI abnormalities occur." (PMID 31083399, 2019).
cardiac amyloidosis (continued). "Between January 2009 and January 2019 we performed resting transthoracic echocardiography in 55 patients with cardiac amyloidosis: 44 had AL-, 9 TTR (6 with mTTR and 3 with wtTTR), and one patient had AA amyloidosis." (PMID 31878928, 2019). "TTR cardiac amyloidosis is characterized by progressive infiltrative, restrictive cardiomyopathy with diastolic dysfunction (HFpEF) causing right-sided heart failure in early stages and deterioration of left systolic ejection fraction later on." (PMID 31083399, 2019). "Even though orthotopic liver transplantation has proven successful in patients with FAP, it has been less effective in TTR cardiac amyloidosis with evidence of worsening cardiomyopathy due to post-implantation progressive deposition of native TTR." (PMID 31083399, 2019). "At present, treatment of TTR cardiac amyloidosis mainly follows current guidelines for the management of heart failure and arrhythmias because research has primarily concentrated on studying the effects on FAP and less on ATTR cardiomyopathy." (PMID 31083399, 2019). "Technetium pyrophosphate scintigraphy indicated marked diffuse myocardial uptake of technetium pyrophosphate, strongly suggesting transthyretin cardiac amyloidosis, which was firmly confirmed by a left ventricular endomyocardial biopsy." (PMID 30553273, 2018). "Proteomic typing demonstrated that this patient had TTR cardiac amyloid, and genetic studies demonstrated the TTR gene to be wild-type, so-called senile cardiac amyloidosis." (PMID 29795248, 2018). "Based on these results, 18F-florbetaben has also been evaluated for cardiac amyloidosis and found it was able to accurately identify and differentiate between cardiac amyloidosis (both Al and TTR) and hypertensive heart disease." (PMID 30043115, 2018). "There were no statistical significant differences in age of controls, heart failure and TTR group but the patients affected with senile cardiac amyloidosis were significantly older than control and TTR group." (PMID 30332417, 2018). "He died at the age of 79 of progressive heart failure 39 months following the diagnosis of TTR cardiac amyloidosis." (PMID 29795248, 2018). "We report a case of rapidly evolving, multichamber thrombi in a patient who was ultimately diagnosed with wild-type TTR cardiac amyloidosis." (PMID 30671265, 2018). "Technetium pyrophosphate (99mTc-PYP) scintigraphy indicated marked diffuse myocardial uptake of 99mTc-PYP, which strongly suggested TTR cardiac amyloidosis." (PMID 30553273, 2018). "In anotherstudy, Tafamidis resulted in stabilization of transthyretin in 97% of patientswith mild to moderate HF due to the wild type of cardiac amyloidosis." (PMID 28678923, 2017). "One cohort evaluated the tolerance andeffects promoted in 13 patients with cardiac amyloidosis by TTR, both mutant andwild type." (PMID 28678923, 2017). "TTR silencers using either small interfering RNA (siRNA) or oligonucleotides specific for silencing TTR production have shown remarkable ability to lower TTR to >80% of normal levels in subjects with TTR cardiac amyloidosis." (PMID 26918183, 2016). "This has led to the multiple clinical studies underway testing pharmacological interventions to stabilize the common TTR misfolding in cardiac amyloidosis." (PMID 26664897, 2015). "Along this line of evidence, examination of a heart specimen from a patient diagnosed with amyloid cardiomyopathy revealed substantial heparan sulfate accumulation in TTR amyloid deposits." (PMID 25950566, 2015). "TTR-related cardiac amyloidosis is thought to be vastly underdiagnosed, particularly when neurologic involvement is mild or absent." (PMID 23425518, 2013). "Third, although this is one of the largest series comparing biomarkers of cardiac amyloidosis in AL‐CMP versus TTR‐CMP, the number of subjects is still relatively small." (PMID 23537813, 2013).
cardiac amyloidosis (continued). "In our experience, cardiac disease occurs in approximately 50% of patients with TTR-FAP, with most TTR mutations causing amyloid cardiomyopathy." (PMID 23425518, 2013). "Her brain natriuretic peptide (BNP) level was elevated to 892.9 pg/mL, ^99mTc-pyrophosphate scintigraphy demonstrated myocardial tracer uptake, and gastrointestinal endoscopic biopsy demonstrated transthyretin amyloid deposition, confirming transthyretin cardiac amyloidosis (ATTR)." (PMID 41531937, 2026). "The matrix analysis organized input from all stakeholders, allowing for the creation of a system map that reveals the complexity of the transthyretin cardiac amyloidosis testing process and potential implementation strategies to improve the efficiency and effectiveness of the system." (PMID 41544075, 2026). "Additionally, we seek to synthesize the relevant outcomes and safety data of TTR silencing therapies and how they relate to circulating vitamin A levels and vitamin A-related clinical outcomes in a manner that is relevant to the cardiac amyloidosis specialist." (PMID 42188091, 2026). "Overall, scintigraphy identified cardiac amyloidosis (CA) in 8.2% of relatives, while 20.5% carried a pathogenic transthyretin variant without radiotracer uptake, with Phe53Leu being predominant." (PMID 39537877, 2025). "On a video-level analysis of the YNHHS emergency department POCUS cohort, the view-agnostic model reached higher discrimination compared with view-specific models for hypertrophic cardiomyopathy (δ[AUROC] of 0·03 [95% CI 0·00–0·06]) and transthyretin amyloid cardiomyopathy (0·15 [0·10–0·21])." (PMID 39890242, 2025). "However, the presence of abnormal monoclonal proteins poses a diagnostic dilemma and warrants further evaluation with tissue biopsy and mass spectrometry analysis to differentiate between AL and TTR cardiac amyloidosis." (PMID 41024906, 2025). "Observational multicenter study of stable wild-type transthyretin amyloid cardiomyopathy patients from different cohorts using the Abbott Architect Stat hs-cTnI assay and the Beckman Coulter Access hs-cTnI assay (testing cohorts) and the Siemens Centaur XPT hs-cTnI assay (validation cohort)." (PMID 40371473, 2025). "We report 3 cases of individuals who were initially diagnosed and treated for isolated CS based on multimodality cardiac imaging and later definitively reclassified to wild-type transthyretin cardiac amyloidosis from histopathology obtained by endomyocardial biopsy." (PMID 40645707, 2025). "Additionally, treatments for cardiac amyloidosis 164 include transthyretin amyloidosis (ATTR) stabilizers that prevent tetramer dissociation and amyloid formation, such as tafamidis 165, which can reduce TTR production through RNA silencing." (PMID 40756361, 2025). "In a study-level analysis of the held-out testing transthoracic echocardiographic set, our multi-label view-agnostic classifier successfully discriminated hypertrophic cardiomyopathy (AUROC curve 0·95, 95% CI 0·94–0·96) and transthyretin amyloid cardiomyopathy (0·98, 95% CI 0·96–0·99)." (PMID 39890242, 2025). "Our vignette describes an interesting case of progressive heart failure symptoms as initial manifestations of transthyretin cardiac amyloidosis, which could advance hastily to end-stage heart failure if not recognized early." (PMID 40134993, 2025). "Cardiac amyloidosis—particularly transthyretin- and light-chain–related forms—often presents clinically as HFpEF and may progress to acute decompensation." (PMID 40572770, 2025). "Despite this correlation, established treatments for transthyretin cardiac amyloidosis-associated arrhythmias are lacking." (PMID 39816749, 2025). "Notably, 99mTc-PYP scintigraphy showed findings suggestive of transthyretin cardiac amyloidosis (ATTR-CA)." (PMID 41367026, 2025).
cardiac amyloidosis (continued). "Commonly used drugs, such as beta-blockers, calcium-channel blockers, and digoxin, are also known to be poorly tolerated in TTR cardiac amyloidosis patients due to the restrictive filling physiology and heart rate dependence, favoring the adoption of the rhythm control strategy." (PMID 40406766, 2025). "For patients diagnosed with TTR-related cardiac amyloidosis, experts recommend cardiological evaluations every six months (i.e., cardiology visit, ECG, echocardiogram, and laboratory tests including NT-proBNP and local Troponin T-hs o I-hs), and annually (24-h Holter ECG)." (PMID 40948648, 2025). "Both ATTRwt and ATTRv lead to cardiac amyloidosis through transthyretin deposition (ATTR-CA)." (PMID 39981348, 2025). "Additionally, increase of serum TTR concentrations has also been shown to be a prognostic marker in ATTR cardiac amyloidosis patients." (PMID 40067567, 2025). "Given the difference in prognosis and geometry between AL‐CM and TTR‐CM, there may be markedly differences in speckle‐tracking echocardiographic findings between the two cardiac amyloidosis subtypes." (PMID 39873364, 2025). "Providing tools for comprehensively evaluating scintigraphy images could enhance transthyretin amyloid cardiomyopathy (ATTR-CM) diagnosis." (PMID 39907796, 2025). "In particular, this study revealed a higher prevalence of TTR-related cardiac amyloidosis, indicating that regional factors might play a role in genetic variations." (PMID 41010045, 2025). "Cardiac amyloidosis develops due to deposition of amyloid protein in the extracellular space most commonly as a result of light chains from plasma cells (AL amyloidosis) or from misfolding of transthyretin protein (ATTR)." (PMID 39400790, 2024). "Tafamidis has been well‐studied for treating TTR‐related cardiac amyloidosis." (PMID 39096004, 2024). "A Tc-99m pyrophosphate scan excluded transthyretin cardiac amyloidosis." (PMID 40078628, 2024). "This was consistent with the established clinical findings of hereditary TTR cardiac amyloidosis." (PMID 39316441, 2024). "Furthermore, a clinical case series study reported important findings in three patients with transthyretin (TTR) cardiac amyloidosis (CA) who had concomitant severe AS." (PMID 39064103, 2024). "In May 2021, a 99mTc-DPD scintigraphy was performed, showing ‘increased myocardial uptake’ of high intensity (Perugini grade 3/3), demonstrating a scintigraphic pattern compatible with cardiac amyloidosis due to TTR (ATTR)." (PMID 39157068, 2024). "ATTRwt is the most prevalent form of transthyretin amyloid cardiomyopathy, primarily affecting individuals over the age of 60 with an average age of 80 years and is characterized by the natural tendency of wild-type TTR to aggregate and form harmful amyloid fibrils." (PMID 39451564, 2024). "Incorporation of TTR levels in the screening programs for hereditary cardiac amyloidosis may be especially beneficial considering that the V142I variant is a common genetic variant with a carrier prevalence of 3–4% among Black individuals." (PMID 39043640, 2024). "Transthyretin (TTR) produces one of the most common forms of cardiac amyloidosis." (PMID 39157068, 2024). "Similarly, cardiac amyloidosis (CA), especially “wild-type transthyretin” (wTTR), has shown a prevalence rate ranging from 22% to 25% in people older than 80 years." (PMID 36998972, 2023). "According to a study, using information from medical claims, a random forest machine learning model may spot prospective cases of wild-type transthyretin amyloid cardiomyopathy." (PMID 36982754, 2023). "In TTR and AL cardiac amyloidosis, heart failure is a major issue." (PMID 37600055, 2023). "However, there is no information on vascular function in patients with wild-type transthyretin amyloid cardiomyopathy (ATTRwt-CM)." (PMID 37048618, 2023).
cardiac amyloidosis (continued). "The disease can be divided into two categories, wild-type ATTR cardiac amyloidosis (wtATTR-CA) and hereditary transthyretin cardiac amyloidosis (hATTR-CA), according to the presence or absence of a transthyretin (TTR) mutation." (PMID 36776255, 2023). "To date, diagnosing and treating transthyretin cardiac amyloidosis remains challenging." (PMID 36829983, 2023). "Similarly, myocardial edema was detected in cardiac amyloidosis (CA), both light chain (AL) and transthyretin (ATTR)." (PMID 37623332, 2023). "Transthyretin amyloid cardiomyopathy has been extensively studied in high-income countries, but the available research in low and middle-income countries (LMICs) may be more limited." (PMID 37901600, 2023). "Currently, only scattered TTR variants were found in China, and most of them were associated with familial amyloid polyneuropathy, lacking comprehensive analysis and diagnosis of cardiac amyloidosis." (PMID 36776255, 2023). "Furthermore, sudomotor dysfunction has been associated with cardiac function deterioration and poor outcome in patients with wild-type transthyretin cardiac amyloidosis (CA-TTRwt)." (PMID 37256072, 2023). "The main types of cardiac amyloidosis include transthyretin cardiac amyloidosis (ATTR-CA), in which transthyretin (TTR) is the amyloid precursor, and amyloid light-chain cardiac amyloidosis (AL-CA), in which immunoglobulin light chains are the amyloid precursor." (PMID 36768243, 2023). "Hereditary transthyretin cardiac amyloidosis is partly responsible for the high burden of heart failure in people of West African descent, given that the most common mutation of the transthyretin protein accountable for the disease occurs with a high allelic frequency in that population." (PMID 39681929, 2023). "Furthermore, evidence exists of the presence of microcalcification in transthyretin (ATTR) cardiac amyloidosis, which is often imaged with certain [99mTc]Tc-BPs48, but is less well detected by [18F]NaF49,50." (PMID 37669973, 2023). "Cardiac amyloidosis is accompanied by fibrosis and wall stiffness, which may be partially explained by the finding that cardiac fibroblasts cultured on deposited TTR fibrils had increased proliferation and migration rates." (PMID 35262277, 2022). "TTR amyloid cardiomyopathy is characterized by progressive deposition of TTR amyloid fibrils." (PMID 37123434, 2022). "The current diagnosis of cardiac amyloidosis (CA) usually refers to thedeposition of fibrils composed of monoclonal immunoglobulin light chains (AL) ormisfolded monomers of transthyretin (ATTR), secondary to hereditary (ATTRh) oracquired wild-type (ATTRwt) mutations." (PMID 39077150, 2022). "However, more than 98% of amyloid cardiomyopathies are due to light chain monoclonal immunoglobulins (AL) and fibrilar transthyretin (ATTR)." (PMID 35204645, 2022). "Notably, tafamidis, a pharmacological transthyretin-stabilizer, improved outcome of patients affected by transthyretin-related cardiac amyloidosis, a progressively more recognized clinical phenotype of HFpEF." (PMID 34273070, 2022). "We aimed to ascertain the real-world diagnostic accuracy of bone scintigraphy in combination with free light chain (FLC) assessment for transthyretin (ATTR) cardiac amyloidosis (CA) using the histopathological diagnosis derived from endomyocardial biopsy (EMB) as a reference standard." (PMID 36551808, 2022). "Thus, the presence of transthyretin cardiac amyloidosis can be suspected based on various red flags, especially apical sparing, in severe AS patients who have been referred for transcatheter aortic valve implantation or surgical aortic valve replacement." (PMID 33460030, 2021). "Loss of all components of atrial function characterizes cardiac amyloidosis regardless of the etiology (light chain, mutant or wild-type transthyretin)." (PMID 35096989, 2021).